HAS2 (hyaluronan synthase 2)
Diseases named in the same sentence as HAS2 in open-access papers (continued):
Sharing a sentence is not in itself a finding about the gene and the disease.
prostate carcinoma (8 papers, 2011 to 2026). A carcinoma that arises from epithelial cells of the prostate gland. "Studies in PC3 prostate cancer cells have shown that WISP1-induced β-catenin signaling has been linked to HAS2 transcription, suggesting a coordinated regulation of hyaluronan metabolism and MMP activity during ECM remodeling." (PMID 41597235, 2026). "HAS2, which encodes hyaluronan synthase 2, is overexpressed in multiple tumor types, including breast and prostate cancer, and HAS2 reportedly promotes cancer cell invasion and metastasis." (PMID 27977763, 2016). "This indicates that more aggressive prostate cancer cells invade the lymphatic vessels, as they expressed more HAS2." (PMID 30705401, 2019). "Overexpression of either HAS2 or HAS3 in several tumour types such as prostate cancer, breast cancer, osteosarcoma and colon carcinoma is known to be associated with higher malignancy or metastasis." (PMID 21429221, 2011). "Co-immunofluorescent staining for HAS2 and LYVE-1 showed that a portion of prostate cancer cells that localized in the lymphatic vessels expressed dramatically higher levels of HAS2, with significant differences in the level of HAS2 in prostate cancer cells outside or inside the lymphatic vessels." (PMID 30705401, 2019). "Interestingly, in a mouse model of prostate cancer, co-expression of aHyal-1 and a HAS-2 significantly increased angiogenesis." (PMID 26352698, 2015). "Finally, a correlation between high coexpression of HAS2 and HYAL1 and strong tumour growth and angiogenesis was observed for prostate carcinoma." (PMID 35767191, 2022). "Overexpression of HA synthase 2 (HAS2) increases receptor tyrosine kinase-dependent signaling in breast and colon cancer cells, whereas antisense-mediated suppression of HAS2 inhibits tumorigenesis and progression of breast and prostate cancers." (PMID 26448753, 2015). "Interestingly, in a mouse model of prostate cancer, co-expression of a hyaluronidase (HYAL1) and a hyaluronan synthase (HAS2) significantly increased angiogenesis." (PMID 23560496, 2013). "In addition, in prostate carcinoma HAS3 and HAS2 have been shown to produce HA that is broken down by Hyal1 and that subsequently drives tumour progression and even metastasis." (PMID 21429221, 2011).
asthma (6 papers, 2016 to 2021). "Our previous genome-wide association study reported that hyaluronan synthase 2 gene (HAS2) is a novel candidate gene for susceptibility to adult asthma." (PMID 35069543, 2021). "Our previous study identified HAS2 as a candidate gene for increased susceptibility to adult asthma." (PMID 35069543, 2021). "The roles of the various enzymes during inflammation have not been delineated, but a recent genome wide association study has shown HAS2 is a susceptibility gene for asthma in a Japanese population." (PMID 29966020, 2018). "Our findings take seemingly disparate risk factors and features of asthma, namely NO, HA (HAS2), ER stress (ORMDL3) and SMCs and demonstrate their interactions." (PMID 29966020, 2018). "The ability of HAS2 to generate leukocyte-binding HA cables in response to NO may contribute to its association with asthma." (PMID 29966020, 2018). "Furthermore, epithelial regulation of airway HAS2 may influence the susceptibility of children with asthma to experience severe exacerbations." (PMID 30361541, 2018). "Collectively, these results indicate that IL-17 is required to drive steroid resistance intractable to asthma development in Has2+/− mice." (PMID 35069543, 2021). "Because high-molecular-weight hyaluronan (HMW-HA) is thought to have an anti-inflammatory function, HAS2 dysfunction was thought to exacerbate asthma." (PMID 35069543, 2021). "In this study, the development of airway remodeling after repeated allergen challenges in Has2+/− mice was analyzed to clarify the role of Has2 in the pathogenesis of airway remodeling in asthma." (PMID 35069543, 2021). "Hyaluronan synthase-2 (HAS-2) is a major enzyme responsible for HA synthesis and has recently been shown to be a susceptibility gene for asthma." (PMID 29966020, 2018). "Therefore, this study aimed to clarify the Has2 dysfunction, triggering severe airway remodeling and steroid insensitivity in a murine model of asthma." (PMID 35069543, 2021). "Furthermore, it has been reported that the mRNA expression of hyaluronan synthases (HAS1 and HAS2) was upregulated in a murine model of asthma, and the production of ROS can be detected within 2 h after the stimulation of ozone on airway epithelium." (PMID 29284473, 2017).
atherosclerosis (6 papers, 2013 to 2024). A disease characterized by the build-up of fatty material and calcium deposition in the arterial wall resulting in partial or complete occlusion of the arterial lumen. "In addition, it contributes to the progression and increased disruption of vascular integrity in atherosclerosis, which is associated with an overexpression of HAS2." (PMID 38473817, 2024). "In accordance with higher HA levels, the upregulation of HAS, predominantly that of HAS2, contributes to the progression of cardiovascular diseases like atherosclerosis." (PMID 38473817, 2024). "In a previous study, we observed more pronounced atherosclerosis in the aorta of the HAS-2 transgenic mice." (PMID 37176139, 2023). "In a previous study, hyaluronan overexpression in the tunica media of HAS-2 transgenic mice was found to promote the development of atherosclerosis in ApoE−/− mice." (PMID 37176139, 2023). "The identification of the selective actions of homo-IR that can be inhibited by IGF1R is exciting especially with the identification of a IR-specific downstream target, Has2, which has already shown to be important for restenosis and possible atherosclerosis." (PMID 31562314, 2019). "Vessel renarrowing after surgical intervention and atherosclerosis remain significant clinical problems, and HA/HAS2/SMILR have emerged as key components of these pathological processes." (PMID 27052414, 2016). "Indeed, in a transgenic mouse model with vascular smooth muscle overexpression of HAS-2 followed by hyaluronan accumulation, accelerated atherosclerosis occurred when this mouse was cross-bred with ApoE−/− mice." (PMID 37176139, 2023). "Chai and colleagues generated mice overexpressing human HAS2 under the control of the αSMA promoter, and crossed these mice with apoE–/– mice, and showed that overproduction of HA in the aorta of apoE–/– mice accelerated the development of atherosclerosis." (PMID 23484050, 2013). "Although male-specific endothelial dysfunction in the current study could explain the increased atherosclerosis in HAS2 transgenic mice, further investigations using other approaches are required to address whether EC dysfunction accelerates atherosclerosis in HAS-2 transgenic mice." (PMID 37176139, 2023).
colorectal cancer (6 papers, 2020 to 2023). A primary or metastatic malignant neoplasm that affects the colon or rectum. "Interestingly, HAS-2 has recently been found as an important promoter of malignant phenotype in colorectal cancer cells through enhancing metastatic capacity, resistance to cell death, epithelial-mesenchymal transition, among other functions." (PMID 34136383, 2021). "Therefore, malignancy driver functions attributed in our work to p32 in colorectal cancer cells could be explained at least partly by its ability to significantly modify the transcription levels of HAS-2 and PDCD4 genes, and to its ability to activate the PI3K/Akt/mTOR signaling pathway." (PMID 34136383, 2021). "Among the five ligands that were found only in MC tissues, bone morphogenetic protein 4 (BMP4), hyaluronic acid synthase 2 (HAS2), and heparin-binding epidermal growth factor-like growth factor (HBEGF) were reported to be involved in cell proliferation or cell migration in colorectal cancer." (PMID 37091868, 2023).
glioma (6 papers, 2018 to 2025). A benign or malignant brain and spinal cord tumor that arises from glial cells (astrocytes, oligodendrocytes, ependymal cells). "This study indicates that elevated expression of HAS2 is associated with glioma progression and suggests that HAS2 has a prognostic significance in diffusely infiltrating astrocytomas." (PMID 29914429, 2018). "Similarly, in glioma models, HAS2 overexpression enhances malignancy and reduces ferroptosis via Wnt/β-catenin–dependent pathways." (PMID 41461315, 2025). "Latrunculin A was previously shown to reduce HAS2 expression in fibroblasts, and sorafenib was shown to reduce CREB3L2 expression in glioma cells." (PMID 32898143, 2020). "HAS2 expression is regulated both at the transcriptional and translational levels; for instance, in response to PDGF-BB and phorbol 12-myristate 13-acetate (PMA), but also through the long non-coding RNA HAS2-AS1 that is elevated in gliomas." (PMID 35954411, 2022). "Overexpression of HAS2 in murine astrocytoma cell lines, unable to produce hyaluronidases, decreased cells capability to form subcutaneous or intracranial tumors, indicating that the activity of both HAS and HYAL are essential for glioma cell invasion." (PMID 29914429, 2018). "Moreover, glioma cell viability was not significantly affected when HAS2 was knocked down or HAS1 was overexpressed." (PMID 33986244, 2021). "Moreover, in view of HAS1, HAS2, and HAS3 expression in glioma, we over-expressed HAS1 and knocked down HAS2 in glioma cell lines, the results demonstrated the over-expression of HAS1 or the silencing of HAS2 did not significantly affect the viability of glioma cells." (PMID 33986244, 2021).
bladder cancer (5 papers, 2015 to 2021). "This revealed that bladder cancer cells whose aggressive growth is mediated by loss of AGL are susceptible to apoptosis with loss of HAS2, CD44 or RHAMM." (PMID 27595989, 2016). "We have established that loss of AGL promotes rapid bladder cancer growth via HAS2-HA-CD44/RHAMM pathway." (PMID 27595989, 2016). "We have earlier shown that loss of AGL induces rapid growth of bladder cancer cells via HAS2 mediated HA synthesis." (PMID 27595989, 2016). "Higher amounts of cleaved Cas3, Cas9 and PARP was observed in AGL low bladder cancer cell with loss of HAS2, CD44 or RHAMM." (PMID 27595989, 2016). "Our experiments with T24T bladder cancer cells show that 15 to 18 % of T24T shCTL and shAGL cells undergo apoptosis with loss of HAS2." (PMID 27595989, 2016). "This also provides evidence that CD44 and RHAMM are involved in HAS2/HA signaling in bladder cancer cells with loss of AGL." (PMID 27595989, 2016). "Moreover knockdown of HAS2, CD44 and RHAMM reduced growth and induced apoptosis predominantly in the AGL knockdown bladder cancer cells confirming that loss of AGL drives bladder cancer growth via HAS2/HA/CD44-RHAMM axis." (PMID 27595989, 2016). "We have previously established that loss of AGL drives aggressive bladder cancer growth via HAS2 mediated HA synthesis and provided preclinical evidence that targeting the HAS2/HA axis is possibly therapeutically beneficial for bladder cancer patients with low AGL expression." (PMID 27595989, 2016). "HNF4G activated the transcription of HAS2 by interacting with the promoter/enhancer region of HAS2 to promote the growth and invasion of bladder cancer cells." (PMID 34819492, 2021). "TUNEL staining showed more apoptotic cells with loss of HAS2, CD44 or RHAMM in AGL low bladder cancer cells." (PMID 27595989, 2016). "These experiments show that loss of HA synthesis by genetic alteration (inhibition of HAS2 expression) or by an inhibitor (4MU) or addition of superfluous HA have little effect on CD44 and RHAMM expression in UMUC3 and T24T bladder cancer cells." (PMID 27595989, 2016). "Loss of Amylo-alpha-1-6-glucosidase-4-alpha-glucanotransferase (AGL) drives rapid proliferation of bladder cancer cells by upregulating Hyaluronic acid(HA) Synthase (HAS2) mediated HA synthesis." (PMID 27595989, 2016). "MGHU4 bladder cancer cells, with loss of AGL, have shown rapid growth driven by the HAS2/HA axis." (PMID 27595989, 2016). "Next we looked into cellular apoptotic pathway with loss of HAS2 in bladder cancer cells with and without AGL." (PMID 27595989, 2016). "In bladder cancer, one recent study found that HNF4G is a most frequently upregulated gene and its overexpression could promote bladder cancer growth and invasion through regulating the hyaluronan synthase 2 gene." (PMID 25878394, 2015). "Our findings strongly point to the importance of the HAS2-HA-CD44/RHAMM pathway for rapid growth of bladder cancer cells with loss of AGL and provides rational for targeting this pathway at various steps for “personalized” treatment of bladder cancer patients based of their AGL expression status." (PMID 27595989, 2016). "Since loss of HAS2 induced apoptosis predominantly in the rapid growing shAGL bladder cancer cells we decided to investigate whether loss of the two dominant HA receptor CD44 and RHAMM, result in similar apoptotic induction of shAGL bladder cancer cells." (PMID 27595989, 2016). "We observed higher HAS2 expression in UMUC3 and T24T shAGL cells and the siHAS2 reduces its expression in the shCTL and shAGL bladder cancer cells." (PMID 27595989, 2016). "Moreover, combined use of HAS2 and HYAL-1 hyaluronidase was able to predict bladder cancer diagnosis and prognosis." (PMID 32862195, 2021). "Western blot analysis and Terminal deoxynucleotidyl transferase (TdT) dUTP Nick-End Labeling (TUNEL) assay was carried out to study cellular apoptosis with HAS2, CD44 and RHAMM loss in bladder cancer cells with and without AGL expression." (PMID 27595989, 2016).
bladder cancer (continued). "Interestingly loss of HAS2 does not reduce expression of CD44 and RHAMM in bladder cancer cells irrespective of AGL expression status." (PMID 27595989, 2016). "Interestingly when we knocked down HAS2 or treated with 4MU, UMUC3 and T24T bladder cancer cells +/− AGL expression had no change in their CD44 and RHAMM expression." (PMID 27595989, 2016).
triple-negative breast carcinoma (5 papers, 2017 to 2025). An invasive breast carcinoma which is negative for expression of estrogen receptor (ER), progesterone receptor (PR), and human epidermal growth factor receptor 2 (HER2). "The human triple negative breast cancer (TNBC) cell line Hs578T highly expresses HAS2 and produces high molecular weight HA which drives cell survival and invasion." (PMID 32774770, 2020). "It was previously shown that HAS2 is crucial for creating a pro-metastastic microenvironment allowing triple-negative breast cancer cells to efficiently colonize to the bone." (PMID 28086235, 2017). "Interestingly, the aggressive claudin-low subtype of triple-negative breast cancers showed high expression of HAS2, CD44 and ZEB1." (PMID 28086235, 2017). "It was shown that increases in the expression of HAS2, HYAL1-2, VEGF and ABCC2 were related to worse prognosis in patients with triple-negative breast cancer (HR: 1.11, 1.14, 1.24, 1.83 and 1.09 respectively)." (PMID 33572239, 2021).
breast tumors (4 papers, 2020 to 2024). "In breast tumors, CSCs upregulate the enzyme hyaluronan synthase 2 (HAS2), which is important for the new synthesis of hyaluronic acid, a major polysaccharide component of the ECM." (PMID 34583655, 2021). "In the METABRIC dataset, HAS2 was overexpressed in 27% of all breast tumors, with highest frequency in those subtypes with poor prognosis (Luminal B, HER2+ and Basal-like)." (PMID 32774770, 2020). "Alterations in HAS1 (< 2%) and HAS3 (6%) were rare, suggesting that HAS2 is the most relevant HA synthase in breast tumors." (PMID 32774770, 2020). "Since several prometastatic genes (Plau, Mmp2, Mmp9, Has2, and Has3) were downregulated in Mbd2-KO PyMT tumors, we next used formalin-fixed lung tissue sections collected at the experimental endpoint and stained them with hematoxylin and eosin (H&E) to assess breast tumor metastasis to the lung." (PMID 38556549, 2024).
colon cancer (4 papers, 2015 to 2021). "HAS2 expression is regulated by Wnt/β-catenin signaling, and LEF1 overexpression increases HAS2 mRNA expression in colon cancer cell lines by through its multiple binding sites on the promoter region of HAS2." (PMID 28757546, 2017). "In a previous study, inhibition of hyaluronan (HA) synthase-2 (HAS2), a biosynthetic enzyme of hyaluoran which is known as one of MMP7 regulators, was shown to decrease MMP7 expression under the condition of HAS2 inhibition and consequently inhibit the invasion ability of colon cancer cells." (PMID 28757546, 2017).
endometrial cancer (4 papers, 2011 to 2024). Primary or metastatic malignant neoplasm involving the endometrium (mucous membrane that lines the endometrial cavity). "For instance, the upregulation of HAS2 is associated with tumor progression and metastasis in breast, oral, endometrial cancer, and astrocytoma." (PMID 36386154, 2022). "Of the 50 endometrial cancer cases, the positive immunohistochemical expression was found in 29 cases for HAS1, 33 cases for HAS2, and 29 cases for HAS3." (PMID 21904555, 2011).
liver cancer (4 papers, 2025). An epithelial or non-epithelial malignant neoplasm that arises from the liver. "In vivo studies have shown that genetic or pharmacologic inhibition of HAS2 reduces stromal HA levels, alters the immune landscape, and significantly attenuates HCC growth, underscoring the HAS2-HA axis as a promising therapeutic target in liver cancer." (PMID 41155434, 2025). "In liver cancer, myCAFs secrete hyaluronan by overexpressing hyaluronan synthase 2 (HAS2), leading to increased tumour growth." (PMID 39780187, 2025). "Emodin can suppress cell growth through inducing cell cycle arrest at G0/G1, S and G2/M stages, such as G0/G1 arrest in NSCLC cells via hyaluronan synthase 2 (HAS2)-mediated signaling, and S and G2/M phases arrest in liver cancer (Hep G2) cells." (PMID 40490812, 2025).
papillary thyroid cancer (4 papers, 2021 to 2024). "Meanwhile, circRNA_102002 was found to facilitate metastasis of papillary thyroid cancer through regulating the miR-488–3p/HAS2 axis." (PMID 35372340, 2022). "For example, circ_102002 is highly expressed in papillary thyroid carcinoma and promotes cell migration and EMT in thyroid carcinoma cells through the miR-488-3p/HAS2 axis." (PMID 38309290, 2024).
Arthritis (3 papers, 2013 to 2024). Inflammation of a joint. "By dividing SPAID into its component clinical signs, we were able to see that the highest peak of association for both fever and arthritis (27.5–29 Mb) was in strong, but not perfect LD with the peak containing HAS2 (24 Mb, r2 = 0.6–0.8)." (PMID 24130694, 2013). "By modulating the expression and activity of HAS2, tissue repair, inflammatory responses, and the progression of various diseases can be influenced, making HAS2 a potential target for various diseases, including pelvic floor disorders, arthritis, and certain cancers." (PMID 39118664, 2024). "This process is mediated by increased HAS2 and decreased HYAL1 in the synovial membrane, suggesting that HA production is accelerated in arthritis." (PMID 26703073, 2015).